SPATA25 (spermatogenesis associated 25)
Description:
May play a role in spermatogenesis.
Synonyms: C20orf165; TSG23; dJ337O18.8
Tractability: Antibody: UniProt predicts a signal peptide or a membrane-spanning region.
Gene: Protein-coding gene on chromosome 20 (45,886,491 to 45,887,622, reverse strand). Ensembl gene ENSG00000149634.
Subcellular location: Membrane
Subcellular location (Human Protein Atlas): Golgi apparatus
Gene Ontology:
Molecular function: protein binding
Biological process: spermatogenesis
Cellular component: membrane
Genetic constraint (gnomAD): Loss-of-function variants: 16 observed, 15.96 expected, observed/expected ratio (o/e) 1, 90% interval 0.68 to 1.52. The upper end of that interval is the gene's LOEUF score, 1.52, which puts it in group 6 of 6, group 1 being the genes least tolerant of losing a copy. Missense variants: 285 observed, 298.11 expected, observed/expected ratio (o/e) 0.96, 90% interval 0.87 to 1.05. Synonymous variants: 115 observed, 123.6 expected, observed/expected ratio (o/e) 0.93, 90% interval 0.8 to 1.09.
Homologues: Orthologues: chimpanzee SPATA25 (97% identical), macaque SPATA25 (97% identical), dog SPATA25 (81% identical), rat Spata25 (81% identical), mouse Spata25 (79% identical), pig SPATA25 (79% identical), guinea pig SPATA25 (75% identical), rabbit SPATA25 (69% identical).
Diseases named in the same sentence as SPATA25 in open-access papers:
SPATA25 is named in the same sentence as 2 diseases in open-access papers, as found by Europe PMC text mining. Sharing a sentence is not in itself a finding about the gene and the disease. The quoted sentences say what the papers report.
Azoospermia (1 paper, 2023). Absence of any measurable level of sperm,whereby spermatozoa cannot be observed even after centrifugation of the semen pellet. "Spata25 expression was significantly decreased in patients with obstructive azoospermia and in testis of an azoospermic mouse model, suggesting its role in spermatogenesis." (PMID 36834539, 2023).
SPATA25 also shares sentences with these, for which no sentence is quoted: Globozoospermia (1 paper).